ENSG00000261582 (novel transcript)
Gene: Protein-coding gene on chromosome 20 (35,267,885 to 35,280,043, reverse strand). Ensembl gene ENSG00000261582.
Genetic constraint (gnomAD): Missense variants: 92 observed, 122.44 expected, observed/expected ratio (o/e) 0.75, 90% interval 0.63 to 0.89. Synonymous variants: 44 observed, 44.68 expected, observed/expected ratio (o/e) 0.98, 90% interval 0.77 to 1.27.